RNF228 (ring finger protein 228)
Synonyms: AC010980.1
Gene: Protein-coding gene on chromosome 2 (222,314,148 to 222,320,155, reverse strand). Ensembl gene ENSG00000288658.
Subcellular location: Membrane
Gene Ontology:
Molecular function: ubiquitin protein ligase activity
Biological process: protein ubiquitination
Cellular component: membrane
Homologues: Orthologues: pig RNF228 (79% identical), mouse Gm2102 (77% identical), rabbit RNF228 (73% identical), tropical clawed frog RNF228 (32% identical), Drosophila melanogaster roq (20% identical). Paralogues in human: RC3H1 (24% identical), RC3H2 (23% identical), RNF182 (13% identical), RNF224 (10% identical), RNF227 (10% identical).